BCL2 (BCL2 apoptosis regulator)
Diseases named in the same sentence as BCL2 in open-access papers (continued):
Sharing a sentence is not in itself a finding about the gene and the disease.
leukemia (continued). "Therefore, it is not surprising that the targeting of OXPHOS via the BCL-2 inhibitor venetoclax in combination with the hypomethylating agent azacitidine was able to impair leukemia stem cells (LSCs) proliferation and metabolic activity." (PMID 30834247, 2019). "Noteworthy, we found that BCR activation was able to restore the expression of BCL2 to basal levels in isolated CLL cells treated with the mithralog, further supporting the pro-survival role of anti-IgM by antagonizing the pro-apoptotic activity of EC-7072 against leukemia cells." (PMID 31681329, 2019). "In addition, TW-37 markedly downregulated the expression of Bcl-2 protein, while not affecting Bcl-xL or myeloid cell leukemia-1." (PMID 32257914, 2019). "Similarly to the leukemia, we suppose that there is initiation of apoptosis at least at the level of activated transcription of the BAX gene, but at the same time there is inhibition of apoptosis because of elevated levels of Bcl-2." (PMID 29515335, 2018). "While the mechanism of Bcl-2 expression in CSC chemo/drug resistance is still unclear, and it might be due to chromosomal translocation or another pathway, it was demonstrated that leukaemia CD34+ cells expressed Bcl-2 and Bcl-X, and Bcl-2 was highly expressed in breast CD44+/CD24−/low CSCs." (PMID 27825361, 2016). "Within 13 days, the recipient mice treated with vehicle control rapidly succumbed to leukemia irrespective of whether they were transplanted with p185+ B-ALL cells re-programmed with human BCL-2 or human MCL-1." (PMID 26862853, 2016). "Novel transferrin receptor-targeted liposomes delivered phosphorothioate antisense oligodeoxyribonucleotide (ODN-G3139) in TfR positive K562 leukemia cells and downregulated Bcl-2 protein in K562 cells 2-fold greater than non-targeted liposomes and 10-fold greater than free G3139." (PMID 25071577, 2014). "If this is a general phenomenon in other leukemias, this might explain the lack of therapeutic efficacy with Bcl2 antagonists in leukemia." (PMID 24223100, 2013). "We identified a singular MLL-specific hyperactivated pathway that through AMPK phosphorylation leads to the activation of BCL-2, a well known anti-apoptotic regulator crucial for chemotherapy resistance already found to be over-expressed both at mRNA and protein levels in MLL-rearranged leukemias." (PMID 21042412, 2010). "Finally, we selected several types of leukemia (Jurkat: TIB-152, EL4: TIB-39, Daudi: ccl-213, RS4:11: crl-1873) and solid tumor (A549: ccl-185, MGC-803: C6582) cells, which exhibit a relatively decent sensitivity to venetoclax and varied levels of BCL-2/BCL-XL expression." (PMID 38368459, 2024). "Thus, based on our results and the drug’s mechanism of action, a high expression of BCL2 seems to be common in ATO APL-resistant cells but also required, in this leukemia type, for sensitivity to venetoclax, suggesting that BCL2 expression might be regarded as a biomarker of the response." (PMID 39598439, 2024). "After analyzing the direct interactions between CPs and BCL-2 or BCL-XL proteins by structural and biochemical approaches, we were curious about their functional effects within cells, especially whether CPs could inhibit a wide panel of leukemia and solid tumor cells like small-molecule inhibitors." (PMID 38368459, 2024). "Notably, when we further assessed SF3B1K700E dependent alternative splicing of Ppp2r5a, which was reported to impair apoptosis via post-translational modification of BCL2 in leukaemia, we did not observe significant alternative 3’ss usage or mRNA expression of Ppp2r5a in KPC-Sf3b1K700E tumor cells." (PMID 37823551, 2023). "For example, the downregulation of BCL-2 reflects the loss of addiction to this protein, but the compensatory upregulation of the anti-apoptotic proteins not targeted by venetoclax (BCL-XL and MCL1) is observed in leukemia or cancer cell line venetoclax-treated cells." (PMID 31226848, 2019).
leukemia (continued). "The results indicated that both iASPP and FHL2 highly expressed in some leukemia cell lines, when silenced either FHL2 or iASPP could reduce the cell proliferation, induce cell cycle arrest at G0/G1 phase, and increase cell apoptosis via p21 and Bcl-2 signaling pathways." (PMID 28402264, 2017). "SOX4 also promoted MYC-mediated leukemogenesis in vivo, while neither MYC, BCL2, nor SOX4 alone induced leukemia within 200 days." (PMID 34310280, 2021). "A silencing approach was used for determining BAG1's role in AML, finding that its down-regulation decreased expression of BCL2, BCL-XL, MCL1, and phospho-ERK1/2, all proteins able to sustain leukemia, without affecting the pro-apoptotic protein BAX." (PMID 22016818, 2011). "In summary, both the non-selective BCL-2/BCL-XL inhibitor ABT737 and the selective BCL-XL inhibitor A1155463 exerted synergism to kill JMML cells in combination with azacitidine, and additionally targeted leukemia-initiating cells better than azacitidine." (PMID 37945692, 2024). "Collective results indicate that BH3 mimetics may not be effective as single agents for paediatric leukaemias, especially as the LPC subpopulations expressed BCL‐2 genes at various levels." (PMID 32452017, 2021). "However, Bcl-2 level, another key anti-apoptotic protein, did not alter in TCC cells treated with CYD 6-17, which was observed from leukemia cells treated with Oridonin." (PMID 27472396, 2016). "Importantly, we have not observed any leukemias in mice reconstituted with HSCs expanded ex vivo with Tat-MYC and Tat-Bcl-2 fusion proteins." (PMID 25170611, 2014). "Interestingly, a survey on the Leukemia MILE Dataset shows that T-ALL primary cells express lower mRNA levels of Bcl2l11 (Bim) compared with healthy bone marrow control tissue while Dnm1l (Drp1), Opa1 and Bcl2 levels do not vary." (PMID 32346136, 2020). "Conversely, BCL2 expression was not modulated by the compound in T cells isolated from patients with CLL, thereby reinforcing the notion that EC-7072 is highly efficient at inducing leukemia cell apoptosis compared to other immune cell subsets in patients with CLL." (PMID 31681329, 2019).
lung carcinoma (543 papers, 1995 to 2026). "Increased resistance to drug-induced apoptosis associated with Bcl-2 expression was observed in mouse 3LL Lewis lung cancer cells overexpressing GM3 ganglioside compared with GM3-negative parental cells." (PMID 38254878, 2024). "p21, caspase-3, and Bcl-2 levels are elevated by biochanin-A, which causes lung cancer to undergo apoptosis." (PMID 38106650, 2023). "in vitro observation on biochanin-A treatment in 95D and A549 lung cancer cells revealed that the level of P21 (cyclin dependent kinase-1), Caspase-3, and Bcl-2 were stimulated causing cell cycle arrest and death." (PMID 38106650, 2023). "The pharmacological BCL2 inhibitors venetoclax and navitoclax phenocopied these effects and caused a cDC1-dependent regression of orthotopic lung cancers and fibrosarcomas." (PMID 37623817, 2023). "Lung cancer cells isolated from clinical specimens overexpressed anti-apoptosis Bcl-2 protein and possessed low susceptibility to available chemotherapy." (PMID 34383763, 2021). "Further, a short peptide derived from Nur77, which induces apoptosis by BCL2 conformational change, inhibited 3D spheroid growth and caused BCL2-dependent apoptosis in a multidrug-resistant lung cancer cell line." (PMID 34758330, 2021). "Altered expression of Bcl-2 genes has been associated with a number of cancers, including melanoma, breast, prostate, chronic lymphocytic leukemia, and lung cancer." (PMID 32392902, 2020). "TGP18 showed transcriptional repression of BCL-2 oncogene causing apoptosis and potential anti-cancer activity in lung cancer xenograft model." (PMID 32929356, 2020). "Consistently, the protein analysis of Mcl-1, Bcl-2, and Bax indicated that treatment of the cells with TM-(–)-18 and TM-(–)-4a caused a dramatic reduction in the Mcl-1 protein in all the primary lung cancer cells." (PMID 32260280, 2020). "Overexpression of prosurvival BCL2 in multiple cancers, such as prostate, ovarian, and lung cancer, is a hallmark for tumorigenesis." (PMID 31583243, 2019). "Based on previous reports, we characterized maritoclax alone and in combination with the BCL-2/xL-specific inhibitor navitoclax in a panel of nine NSCLC cell lines with mutation profiles proportional to that seen in lung cancer patients." (PMID 31150457, 2019). "The overexpression of Bcl-2 in lung cancer cases has been linked to poor prognosis as well as cell survival." (PMID 31817718, 2019). "In lung cancer, the expression of variants of the Bcl-2 family has been described, for instance the presence of Bcl-2 and Bcl-XL is associated with an anti-apoptotic phenotype in non-small cell lung carcinoma." (PMID 30149660, 2018). "In agreement with our findings, TFP has been shown to induce apoptosis in A549 lung cancer cell line that is associated with downregulation of anti-apoptotic Bcl-2 protein and upregulation of pro-apoptotic Bax protein." (PMID 27283899, 2016). "Here we have identified a previously unrecognized role of Bcl2 in regulating mtDNA repair and mtDNA mutation in human lung cancer cells." (PMID 26268226, 2015). "Aberrant expression of Bcl2 is associated with many human cancers, such as melanoma, breast, prostate, chronic lymphocytic leukemia, colon, and lung cancer." (PMID 26556865, 2015). "Deregulated expression of Bcl2 is linked to many human cancers, such as melanoma, breast, prostate, chronic lymphocytic leukemia, colon, and lung cancer." (PMID 26556865, 2015). "Stratification analysis for associations between BCL2 rs1564483 (c*1204G>A) genotypes and risk of lung cancer." (PMID 23977251, 2013).
lung carcinoma (continued). "When comparing with the BCL2 rs1564483 GG genotype, subjects with the rs1564483 GA or AA had significantly decreased risk of lung cancer (OR = 0.78 and 0.73, P = 0.016 and 0.038, respectively)." (PMID 23977251, 2013). "In our study, we found that the rs1564483A allele in 3′-UTR of BCL2 gene was associated with reduced lung cancer risk in the male Chinese, and this effect was more evident in the elders, smokers, and subjects without family history of cancer." (PMID 23977251, 2013). "We further constructed the BCL2 haplotypes and assessed their associations with lung cancer risk by using the THESIAS v3.1 software, after adjustment of age, smoking status, pack-years smoked, and family history of cancer." (PMID 23977251, 2013). "We found that the BCL2 3′-UTR rs1564483 A allele has a inverse dose-response relationship with lung cancer risk, which was more evident in the elders, smokers, and subjects without family history of cancer." (PMID 23977251, 2013). "Genotype frequencies of BCL2 among case and control subjects and their associations with risk of lung cancer." (PMID 23977251, 2013). "The apoptotic profile of the lung cancer cells could be investigated using the measurement of the protein expression of the anti-apoptotic B-cell lymphoma-2 protein (BCL-2), and pro-apoptotic Bcl-2-associated protein x (BAX)." (PMID 39821171, 2025). "Research has shown that mutations in Bcl-2 cause many cancers, especially lung cancer." (PMID 36800962, 2023). "The down-regulated Bcl-2 associating with apoptosis induction which was indicated by chromatin condensation and/or nuclei fragmentation and activation of caspase-9 were presented in lung cancer cells after culture with 25 μM norcycloartocarpin for 24 h." (PMID 34383763, 2021). "In conclusion, this study is the first to show that hydroalcoholic extract of C. aronia L. can decrease the viability of lung cancer cells A549 by causing apoptosis, which was associated with decrease levels of Bcl-2, full length PARP-1 and full-length caspase-3 proteins." (PMID 33112559, 2020). "A study reported a serine protease obtained from Nereis virens (NAP) that increased the Bax/Bcl-2 ratio mRNA expression in H1299 lung cancer cells, which may cause Ca2+ overload of the mitochondria and decrease the mitochondrial membrane potential." (PMID 31861952, 2019). "Over-expression of Bcl-2 protein is associated with a poor response to lung cancer treatment." (PMID 26266801, 2015). "Results indicate that paclitaxel-induced apoptosis enhanced by FHIT expression in lung cancer cells might be associated with modulation of Bcl-2-caspase signaling." (PMID 25880193, 2015). "The BCL2 3′UTR rs1564483A allele was associated with a decreased lung cancer risk and better survival for advanced NSCLC in male Chinese, which may offer a novel biomarker for identifying high-risk population and predicting clinical outcomes." (PMID 23977251, 2013). "In conclusion, Our study provide the first evidence and preliminary findings that the rs1564483 A allele located in the 3′-UTR of BCL2 gene was associated with a significantly lower risk of lung cancer in male Chinese and with a favorable prognosis of advanced NSCLC males." (PMID 23977251, 2013). "We hypothesized that genetic variants of BCL2 gene may be associated with lung cancer susceptibility and prognosis." (PMID 23977251, 2013). "Notably, Bcl-2 overexpression makes lung cancer cells resistant to apoptosis caused by DNA damage." (PMID 36230484, 2022).
lung carcinoma (continued). "Since Bcl-2 may play a crucial role in regulating apoptosis and survival of both normal and malignant lung cells, the aim of this study is to investigate whether the genetic variations of BCL2 gene with were associated the susceptibility and survival outcome of lung cancer in male Chinese." (PMID 23977251, 2013). "Similarly, NO-mediated S-nitrosylation of Bcl-2 associated with its ubiquitin degradation could be important in apoptosis resistance and the development of lung cancer induced by Cr(VI) and other carcinogens." (PMID 22629368, 2012). "Possible explanations include the specific cellular context, the co-expression of other pro-apoptotic or anti-apoptotic proteins, or the interaction of Bcl-2 with specific signaling pathways unique to certain lung cancer subtypes." (PMID 40841912, 2025). "Future research should focus on isolating and validating MQLEO’s bioactive components in experimental lung cancer models, elucidating molecular pathways involving Bcl-2 proteins, caspases, and cell cycle regulators." (PMID 40573169, 2025). "This antitumor activity appears to be mediated by the downregulation of Bcl-2 and upregulation of Bax, indicating that AP has potential as a chemical agent for the clinical treatment of lung cancer." (PMID 39945813, 2025). "Accordingly, polyphenon-E (PE) raised the death ratio of lung cancer cells by inhibiting Bcl-2-related apoptosis by reducing the membrane potential of mitochondria and boosting PARP cleavage." (PMID 40867905, 2025). "When the expression of LOXL3 is downregulated, the ubiquitination level of BCL-2 in lung cancer cells increases, while its expression level decreases." (PMID 41250755, 2025). "Research has shown that SCP-1 has a significant growth-inhibitory effect on A549 lung cancer cells; it can arrest the cell cycle in the S phase; and it induced apoptosis in A549 cells through the Bax/Bcl-2 and PI3K/Akt/mTOR signaling pathways." (PMID 40507156, 2025). "Marsdenia tenacissima extract induced apoptosis in lung cancer cells by decreasing caspase-3 zymogens expression/Bcl-2 and increasing caspase-3 activities/Bax." (PMID 41011239, 2025). "Human lung cancer cell lines (A549) were treated with wogonin (0, 5, 15, or 20 μmol/L), and it was found that wogonin significantly improved caspase‐3, downregulated Bcl‐2, and reduced ErbB4 expression." (PMID 41164269, 2025). "On the other hand, the BCL2 protein has been identified three decades ago abnormally overexpressed in some lung carcinomas (37%), whose prognostic value would have an important impact." (PMID 39836700, 2025). "Gedunin has been demonstrated to disrupt the interaction between Hsp90 and key proteins, including Beclin-1 and Bcl-2, thereby inducing increased apoptosis in A549 lung cancer cells." (PMID 40357400, 2025). "NR4A1 is retained in the nucleus through its interaction with T-cell lymphoma invasion and metastasis-inducing protein 1, preventing Bcl-2 activation and contributing to lung cancer cell survival." (PMID 40746844, 2025). "Meanwhile, tumor growth was also inhibited by DAPs in an A549 tumor-bearing mouse model, Bax and caspase-3 were upregulated, and Bcl-2 was downregulated, inducing apoptosis of lung cancer cells." (PMID 39796398, 2025). "Correlation analysis using the cancer tool suggests that FTH1 has a positive correlation with MAP1LC3B and pro-apoptotic protein BAX, whereas it is negatively correlated with the anti-apoptotic protein Bcl2 in lung carcinoma." (PMID 40538534, 2025). "Early in 1998, a study suggested that BCL2 possibly controls the development of tumor angiogenesis with putative mediation by VEGF in lung cancer." (PMID 39735667, 2025). "Deciphering the precise contextual roles of Bcl-2 in lung cancer is crucial for its potential as a therapeutic target or prognostic biomarker." (PMID 40841912, 2025).